CGA (glycoprotein hormones, alpha polypeptide)
Diseases named in the same sentence as CGA in open-access papers (continued):
Sharing a sentence is not in itself a finding about the gene and the disease.
neuroendocrine tumors (continued). "CgA is an intravesicular glycoprotein marker released by neuroendocrine tumours." (PMID 38149143, 2023). "Additionally, among the predicted neuroendocrine neoplasms, seven of 10 cases (70.0%) expressed the classical markers of neuroendocrine cell differentiation (Syn, CgA, and CD56), and four of five cases (80.0%) were INSM1 positive." (PMID 38041048, 2023). "Neuroendocrine tumours have cells capable of producing, storing, and secreting CgA." (PMID 36527470, 2023). "As MTC is a neuroendocrine tumor, CgA is also a reliable biomarker." (PMID 36506082, 2022). "Thus, all neuroendocrine tumour entities can secrete CgA, making CgA an essential marker in neuroendocrine tumour diagnosis." (PMID 36362289, 2022). "Among these, CgA has been found to be more sensitive and specific for various neuroendocrine neoplasms, it correlates with tumor bulk, and may also predict treatment response." (PMID 34830919, 2021). "Serum CgA is routinely used as a biomarker for neuroendocrine tumors." (PMID 32684986, 2020). "Chromogranin A (CgA), synaptophysin (Syn) and the Ki-67 index play significant roles in diagnosis or the evaluation of the proliferative activity of gastroenteropancreatic neuroendocrine neoplasms (GEP-NENs)." (PMID 32917216, 2020). "First, some biochemical markers such as chromogranin A (CgA) and neuron-specific enolase (NSE) maybe useful diagnostic biomarker for neuroendocrine tumor." (PMID 30847618, 2019). "While all granins could be secreted by neuroendocrine tumors, CgA is the only one routinely used in clinical practice: The assay has a high sensitivity and good specificity, and CgA is secreted by most NETs, including malignant ones." (PMID 31382663, 2019). "Thus, although CgA is a widely used serological and histopathological marker for neuroendocrine tumor diagnosis and follow‐up, development of appropriate models is necessary to address the functional role of CgA and its fragments in patients with such tumors." (PMID 31588572, 2019). "It is therefore possible that increased levels of circulating CgA and its fragments, as may occur in the subpopulation of cancer patients with non‐neuroendocrine tumors, can reduce drug delivery to tumor cells, particularly when they are combined with NGR‐TNF." (PMID 31588572, 2019). "CgA is a constitutive secretory product of most neuroendocrine tumors." (PMID 31263455, 2019). "Human Chromogranin A (CgA), a 439-residue-long protein present in the secretory granules of many normal and neoplastic neuroendocrine cells, currently represents the main biomarker for neuroendocrine neoplasms (NENs)." (PMID 29723285, 2018). "Because of the heterogeneity of the disease, neuroendocrine neoplasms secrete a vast spectrum of protein or hormonal markers aside from CgA and 5-HIAA, such as insulin, gastrin, glucagon, somatostatin, growth hormone, calcitonin, substance P, pancreastatin, etc." (PMID 30250431, 2018). "Some evidence suggests that CgA could be useful as a biomarker for neuroendocrine tumors and stress also in dogs." (PMID 28049540, 2017). "In addition, in most neuroendocrine cells, Chromogranin B (CgB) coexists with CgA, and it can be used complementary with CgA as an important marker for detecting neuroendocrine tumors." (PMID 28540290, 2017). "Increased levels of CgA have been identified in the blood of patients suffering from carcinoids or other neuroendocrine tumors, heart failure, renal failure, hypertension, rheumatoid arthritis, and inflammatory bowel disease, indicating an important role of CgA to influence human health and disease." (PMID 28228748, 2017). "A central question that we have yet to answer is whether the neuroendocrine release of CgA in circulation and its fragmentation can affect the biology and progression of non-neuroendocrine tumors." (PMID 27683038, 2016).
neuroendocrine tumors (continued). "Although CgA is a widely studied histopathological and serological marker for neuroendocrine tumors, this is the first evidence that circulating full-length CgA, released in the blood by the neuroendocrine system, has a functional role in non-neuroendocrine tumors." (PMID 27683038, 2016). "Given the limitations of single agent biomarker analysis (CgA), we developed a multi-transcript (n = 51 gene) molecular signature for PCR-blood analysis based on specific neuroendocrine tumor cell transcripts identified by mathematical analysis of 15 NET tissue microarrays." (PMID 25095873, 2014). "In addition, CgA measurement showed a low sensitivity in certain neuroendocrine tumors such as insulinomas, pituitary adenomas and medullary thyroid carcinomas." (PMID 24523932, 2014). "Chromogranin A (CgA), a secretory protein involved in neural cell adhesion and expressed by many neuroendocrine cells, has also been recognized as a useful tissue and serum marker of neuroendocrine tumors." (PMID 26316932, 2011). "Thus, our results support the concept of NB as a neuroendocrine tumor and the suitability of CgA as a NB tumor marker and as an indicator of treatment efficacy." (PMID 19284605, 2009). "Circulating CgA allows early detection of persistent or recurrent neuroendocrine tumours." (PMID 16800893, 2006). "The distribution of NESP55 differs from that of CgA in neuroendocrine tumours." (PMID 12771991, 2003). "We investigated whether plasma chromogranin A (CgA), measured by a new immunoradiometric assay, may be a sensitive and specific marker of phaeochromocytoma and of other neuroendocrine tumours." (PMID 11237384, 2001). "It has been proved to be efficient in measuring CgA levels in patients with neuroendocrine tumours." (PMID 10408695, 1999). "Thus, CgA, either alone or combined with NSE, may be useful to detect patients with neuroendocrine tumour subtypes that are associated with shorter survival and to predict response to certain treatments." (PMID 36527470, 2023). "CHGA, known as Chromogranin A (CgA), a protein stored in the secretory granules of many neuroendocrine cells and neurons, could be detected in the blood of patients with neuroendocrine tumors or heart failure CHGA could also be detected in the serum of some HCC patients." (PMID 36712870, 2022). "Neuroendocrine tumors (NETs) comprise a heterogeneous group of neoplasms derived from enterochromaffin epithelial cells, which retain many structural and functional features of normal endocrine cells, including production of chromogranin A (CgA), synaptophysin, and other peptides." (PMID 26673010, 2016). "The aim of this prospective study was to examine whether discontinuation of proton pump inhibitors (PPIs) or replacement by H2-receptor antagonists (H2RA) resulted in a decrease of chromogranin A (CgA) levels in 196 patients with well-differentiated neuroendocrine tumours (NETs)." (PMID 21989216, 2011). "Plasma CgA in controls (49.0 ± 3.1 ng ml–1, mean ± SE) and in essential hypertensives (50.8 ± 3.5 ng ml–1) was lower (P< 0.0001) than in adrenocortical tumours (91.8 ± 13.2 ng ml–1), in phaeochromocytomas (254 ± 49 ng ml–1) and in patients with other neuroendocrine tumours (469 ± 84 ng ml–1)." (PMID 11237384, 2001). "However, the updated WHO classification discourages the use of CD56 due to its non-specificity for neuroendocrine neoplasms (NENs) and instead advocates for CgA, SYP, and insulinoma-associated protein 1 (INSM1) as novel markers of neuroendocrine differentiation in the head and neck region." (PMID 39937015, 2025). "Instead, the guidelines recommend CgA, SYP, and INSM1 expressions as immunohistochemical markers for neuroendocrine neoplasms of the head and neck region." (PMID 39937015, 2025). "CgA, SYP, and CD56 expressions are routinely checked in surgical diagnostics, and positive immunoreactivity for these markers is commonly observed in neuroendocrine neoplasms." (PMID 39937015, 2025).
neuroendocrine tumors (continued). "IHC revealed CK, SYN and CgA (+) SMA (+) and Syn(+) when they occurred in the gastrointestinal tract, and these tumors were easily misdiagnosed as neuroendocrine tumors." (PMID 40255432, 2025). "Widely recognized as a major marker of neuroendocrine tumor (NET), chromogranin A (CgA) has been found to be related to the clinical deterioration and higher risk of mortality in patients with AHF and CHF." (PMID 37298029, 2023). "Further, 70% of the predicted neuroendocrine neoplasms, a favorable CUP subgroup with specific treatments and good outcomes, were found to express the classical neuroendocrine markers, including Syn, CgA, and CD56." (PMID 38041048, 2023). "CgA and synaptophysin (SPY) are the two most widely used and reliable immunohistochemical markers for neuroendocrine tumors, including MTCs." (PMID 33485291, 2021). "Patients suffering from carcinoids or other neuroendocrine tumors, heart failure, renal failure, hypertension, RA, and IBD display increased levels of circulating CgA, implicating an important role of CgA to influence human health and disease." (PMID 30337922, 2018). "However, patients with non-neuroendocrine tumors may also have abnormal levels of circulating CgA." (PMID 27683038, 2016). "Finally, it is important to say that the observations reported here, obtained with non-neuroendocrine tumor models, cannot be extrapolated to neuroendocrine tumors, as neuroendocrine tumor-derived CgA might reach local concentrations out of the range studied here." (PMID 27683038, 2016). "In the present study, we characterized WE-14 in pheochromocytoma and showed that plasma WE-14 measurement, when used in combination with CgA and EM66, represents a potential new tool for the diagnosis of the different subtypes of this neuroendocrine neoplasm." (PMID 24523932, 2014). "Based on Syn(+) or CgA(+) staining, six stage III patients were diagnosed as neuroendocrine tumor/neuroendocrine carcinoma (NET/NEC) or mixed adenoneuroendocrine carcinoma (MANEC) according to the 2010 World Health Organization (WHO) classification." (PMID 25093184, 2014). "Neuroendocrine markers like CD56, Chromogranin A (CgA), and Synaptophysin (Syn) are usually negative in PH, aiding in its distinction from neuroendocrine tumors despite potential histological similarities." (PMID 39228982, 2024). "It has been shown that CgA is not a sufficiently reliable marker to be used independently in the diagnosis of neuroendocrine tumors." (PMID 39451760, 2024). "These limitations highlight the need for testing CgA selectively (for instance, when a diagnosis has already been established) rather than as a screening tool to rule out the presence of neuroendocrine neoplasms (NENs)." (PMID 38928704, 2024). "In gastric mixed papillary adenocarcinoma-neuroendocrine tumors, there was negative expression of CgA-labeled adenocarcinoma components." (PMID 35785186, 2022). "Irrespective of the primary tumor site, neuroendocrine neoplasms (NENs) share a neuroendocrine differentiation reflected via the expression of CgA, Syn, and neural cell adhesion molecule (NCAM = CD56)." (PMID 34064565, 2021). "Although the specificity of CgA is not good, CgA is the most common non-specific circulating biomarker used for the follow-up of neuroendocrine tumors." (PMID 34868938, 2021). "It is widely acknowledged that CD56 is a sensitive but non-specific marker of neuroendocrine tumors in comparison to Syn and CgA." (PMID 34454530, 2021). "In this context, measurement of plasma CgA, which is the best general plasma marker of neuroendocrine tumors is not recommended for diagnosis of pituitary gonodotroph tumors." (PMID 30853937, 2019). "It is of clinical relevance that despite this high proportion of metastatic disease, CgA failed to accurately identify 44% of patients with neuroendocrine tumors." (PMID 30564197, 2018).
neuroendocrine tumors (continued). "One commonly used protein marker is chromogranin A (CgA), which is elevated and particularly useful in patients with non-functioning neuroendocrine tumors as well as in its ability to indicate poorer prognosis." (PMID 30250431, 2018). "Elevated circulating CgA levels have been demonstrated in serum or plasma of patients with various hormone-secreting or non-hormone secreting neuroendocrine tumors (NETs)." (PMID 24213232, 2012). "The CgA promoter strongly supports E1A protein expression, with efficiency comparable to the wild-type E1A promoter of Ad5 wt, in neuroendocrine tumor cells and expression was not altered by incorporation of miR122 target sequences in the viral genome." (PMID 20111709, 2010). "Furthermore, the absence of CgA staining is consistent with existing literature, where CgA is typically absent in glomus tumors, aiding in their distinction from neuroendocrine tumors." (PMID 39776317, 2025). "The non-specific marker of neuroendocrine tumors is chromogranin A (CgA)." (PMID 41007858, 2025). "However, all were negative for CgA, and this general absence of CgA excludes a major neuroendocrine origin, particularly as most foregut neuroendocrine tumors are typically positive for this marker." (PMID 40692725, 2025). "Of the 11 cases of neuroendocrine neoplasms of the appendix, all patients, except for 2 cases without immunohistochemical examination, were CgA and Syn positive (including 7 cases with NSE positive), consistent with the diagnostic criteria of neuroendocrine tumors." (PMID 37194067, 2023). "Insulinoma-associated protein 1 (INSM1) has been considered as a novel immunostaining marker for neuroendocrine tumors (NETs) and is hypothesized to be more reliable than first-generation NET biomarkers, such as CGA (chromogranin A), SYP (synaptophysin), and CD56 (neural cell adhesion molecule)." (PMID 36531655, 2022). "Chromogranin A (CgA) is a non-specific biomarker excreted by neuroendocrine tumor (NET) cells." (PMID 34868938, 2021). "CgA, Syn, and CD56 are the most frequently used markers of neuroendocrine differentiation, but the expression of one or more of these markers may also be found in a subset of non-neuroendocrine tumors that may obscure the correct diagnosis." (PMID 34454530, 2021). "Since SCLC is classified with neuroendocrine tumors, immunohistochemistry is very important in the diagnosis of SCLC, especially some neuroendocrine markers, such as Synaptophysin (Syn), Chromogranin A (CgA) and CD56 (an alias for neural cell adhesion molecule 1)." (PMID 34168983, 2021). "In contrast to other neuroendocrine tumor localizations, CgA plasma levels are not suitable to diagnose or follow up the wide majority of patients with colorectal NEN since CgA is rarely elevated and does not mirror tumor burden or predict survival in these patients." (PMID 29232390, 2017). "Thus, the expression of NESP55 was different from that of CgA, which was expressed in all neuroendocrine tumours investigated, regardless of hormone production, cellular composition or malignant potential." (PMID 12771991, 2003). "Since the specificity of CgA proved to be excellent, this assay may be useful for diagnosis both of functioning and non-functioning neuroendocrine tumours." (PMID 11237384, 2001). "In this respect, the currently used blood index, chromogranin A (CgA) is relatively non-specific, has low sensitivity, diverse assay interpretations of normality and defines a secretory product as opposed to specific indices of neuroendocrine tumor cell biology." (PMID 25095873, 2014). "Moreover, plasma measurement of CgA may generate false-negative and false-positive test results for the diagnosis of neuroendocrine tumors." (PMID 24523932, 2014). "Additionally, LCA (-) excludes lymphoid tumors, while CD56 (-), CgA (-), INSM1 (-), and Syn (-) eliminate the possibility of neuroendocrine tumors." (PMID 39723371, 2024).
neuroendocrine carcinoma (25 papers, 2012 to 2025). A malignant neuroendocrine neoplasm composed of cells containing secretory granules that stain positive for NSE and chromogranin. "In two of the cases with neuroendocrine carcinomas, the dosage of chromogranin A showed that an increase in CgA values was suggestive and was associated with the imaging appearance of metastases." (PMID 39941198, 2025). "In the PTC area, Tg, Galectin-3, and CK19 are positive, while CT is negative; in the MTC area, most patients have positive CT and CEA, and neuroendocrine cancer markers such as Syn, CgA, and CD56 are mostly positive, while TG is generally negative." (PMID 41323380, 2025). "All of the patients were diagnosed as neuroendocrine carcinoma according to the immunohistochemical staining (IHC) of specific markers, including chromogranin A (CgA), synaptophysin (Syn), CD56, and Thyroid transcription factor-1 (TTF-1)." (PMID 37920164, 2023). "All (100%) identified patients with neuroendocrine carcinoma had synaptophysin expression >50% of tumor cells, while 30 tumors (69.8%) showed CgA expression." (PMID 28118820, 2017). "Serum CgA levels were much higher in patients who classified as neuroendocrine carcinoma, mixed adenoendocrine carcinoma (P = 0.035) and who were on stage IV (P = 0.041)." (PMID 25501094, 2014). "The rate of CgA mRNA positivity in the lymph nodes resected with non-neuroendocrine cancers was 29 of 115 (25%)." (PMID 22720672, 2012). "The histological and immunohistochemical analyses revealed a well-differentiated neuroendocrine carcinoma involving ileum and pancreas, immunoreactive to CgA, synaptophysin, and CD56." (PMID 23009225, 2012). "The false positive rate for detection of CgA mRNA was 19% in non-neuroendocrine cancers, and appeared to be due to occult neuroendocrine differentiation or contamination by normal epithelium during histological processing." (PMID 22720672, 2012). "A liver biopsy revealed metastatic tissue of neuroendocrine carcinoma (CgA+, synaptophysin+, NSE+, CD56+)." (PMID 23009225, 2012). "The non-neuroendocrine cancers were then examined on a case-by-case basis to determine whether the distribution of the remaining 22 (19.1%) lymph nodes with detectable CgA transcripts was related to characteristics of the resected tumor." (PMID 22720672, 2012). "The differences in the positive rates of immunohistochemical markers Syn, CgA, and Ki-67 in different histological types were analyzed by the continuity-correctedchi-square test (GCNED, and MANEC of the stomach and neuroendocrine carcinoma)." (PMID 36035314, 2022). "Immunohistochemistry showed positive staining for synaptophysin (Syn), chromogranin A (CgA), CD56, and CK19, which are characteristics of neuroendocrine carcinoma." (PMID 36017024, 2022). "Some institutions use peripheral blood measurements of chromogranin A (CgA) and neuron specific enolase (NSE) as these have been shown to be elevated in some patients with high grade neuroendocrine carcinoma including SCLC and some LCNEC patients." (PMID 34513663, 2021). "Ad5-based AdVince combined the three targeting strategies (CgA promoter, miR122 target sequences, and PTD) and specifically killed cancer cells for the treatment of liver metastases from neuroendocrine cancer." (PMID 32370135, 2020). "Neuroendocrine proteins including CgA, S-100B protein, synaptophysin, GFAP protein, and neurofilaments, typically located in neural tissues, are commonly used as markers for neuroendocrine carcinomas." (PMID 31263455, 2019). "Neuroendocrine carcinomas are characterized by nuclear heteromorphism and frequent mitosis, and a clear positivity for NSE, CD56, CgA and synaptophysin." (PMID 24932236, 2014). "Still G3 neuroendocrine carcinoma (NEC) are poorly differentiated and show lower expression of CgA, which may affect the Nlrp3/miR-223-related effect described here." (PMID 39851539, 2025).